ACE (angiotensin I converting enzyme)
Diseases named in the same sentence as ACE in open-access papers (continued):
Sharing a sentence is not in itself a finding about the gene and the disease.
angioedema (continued). "By inhibiting ACE, ACE inhibitors increase the accumulation of bradykinin in the plasma, which contributes to the development of angioedema." (PMID 40636633, 2025). "This case underscores the critical importance of maintaining a high index of suspicion for ACE inhibitor-induced angioedema, even in patients with many years of uneventful medication use." (PMID 41035577, 2025). "Unlike ACE inhibitors, ARBs do not increase bradykinin levels in the serum, which was thought to be the primary mechanism behind ACE inhibitor-induced angioedema." (PMID 40636633, 2025). "If patients experience a dry cough or angioedema from ACE inhibitors, angiotensin receptor-neprilysin inhibitors (ARNIs) or angiotensin receptor blockers (ARBs) are recommended." (PMID 40711721, 2025). "This case underscores the importance of recognising atypical, delayed-onset angioedema in patients on long-term ACE inhibitor therapy and supports the evolving role of C1 esterase inhibitors in treatment." (PMID 41035577, 2025). "Bradykinin is also believed to play a central role in the development of angioedema induced by ACE inhibitors." (PMID 40636633, 2025). "Although angioedema is a rare side effect of ACE inhibitors and affects only a small percentage of patients, its clinical significance remains high due to the widespread use of ACEi as a commonly prescribed medication." (PMID 40365500, 2025). "Because angiotensin-converting enzyme (ACE) is a major enzyme responsible for bradykinin catabolism, ACEIs promote angioedema through the accumulation of vasoactive peptides such as bradykinin and substance P." (PMID 40937230, 2025). "This form of angioedema results from bradykinin accumulation due to ACE inhibition, leading to increased vascular permeability and tissue oedema." (PMID 41035577, 2025). "This is thought to be the main mechanism by which ACE inhibitors produce side effects such as angioedema (0.1–0.7% of patients on ACE inhibitors) and a population‐dependent persistent dry cough in 3.9–35% of patients." (PMID 39763019, 2025). "ACE inhibitor-induced angioedema can present even after prolonged and previously uneventful use of the medication." (PMID 41035577, 2025). "Despite no recent medication changes or allergic triggers, clinical assessment suggested angiotensin-converting enzyme (ACE) inhibitor-induced angioedema." (PMID 41035577, 2025). "Strategies aimed at improving physician and patient education regarding ACE inhibitor cessation after primary angioedema, along with proper documentation of adverse drug reactions in medical records are essential." (PMID 40365500, 2025). "ARB-induced angioedema remains less common compared to ACE inhibitor-induced cases but is still a serious condition that can present unexpectedly, even after years of stable medication use." (PMID 40636633, 2025). "A significant and distinct subtype is angiotensin-converting enzyme (ACE) inhibitor-induced angioedema (ACEI-AE), which is estimated to account for up to 30% of all angioedema cases presenting to emergency departments." (PMID 41466925, 2025). "The clinical course of the presented case is highly unusual and includes two rare but severe complications: angioedema induced by an ACE inhibitor perindopril and subsequent post-obstructive negative pressure pulmonary edema, successfully managed with VV-ECMO." (PMID 40365500, 2025). "Angioedema of the face and neck is a rare but potentially life-threatening condition that can arise as an adverse effect of angiotensin-converting enzyme (ACE) inhibitors." (PMID 40636633, 2025). "An estimated 20–30% of ADEs requiring hospitalization have a prominent genetic component, and the frequency of some ADEs (e.g., ACE inhibitor induced angioedema, G6PD related hemolysis) is well-known to vary by ancestry." (PMID 41282679, 2025).
angioedema (continued). "The summary table of ACE inhibitor-induced angioedema case reports highlights the variable clinical presentations, management strategies, and outcomes associated with this potentially life-threatening adverse effect." (PMID 41035577, 2025). "Icatibant, a bradykinin B2 receptor antagonist and C1 esterase inhibitor, commonly used for hereditary angioedema, has shown efficacy in ACE inhibitor-induced cases." (PMID 41035577, 2025). "In this context, we present a noteworthy case that sheds light on a patient’s experience with long-standing ACE inhibitor therapy that was marked by the onset of angioedema shortly after the introduction of sirolimus into the therapeutic regimen." (PMID 38205154, 2024). "Diseases affecting endothelial barrier function also include different forms of angioedema, arising from factors such as allergies, genetic defects, or as a side effect of angiotensin-converting enzyme (ACE) inhibitors." (PMID 38438679, 2024). "We present a rare case of sirolimus potentiated angioedema in a patient with long-standing ACE inhibitor therapy." (PMID 38205154, 2024). "Distinguishing ACE inhibitor-induced angioedema from other types of angioedema, particularly those mediated by bradykinin, requires careful consideration." (PMID 38543146, 2024). "The most affected regions in ACE inhibitor-induced angioedema include the lips, tongue, face, and upper airway." (PMID 38543146, 2024). "Since angioedema due to ACE inhibitors is a result of inhibition of bradykinin degradation (or perhaps other peptides inactivated by ACE), and not bradykinin overproduction, the only agent used to treat HAE that is likely to be effective is Icatibant." (PMID 38332896, 2024). "Further research is needed to characterize the effect of SARS-CoV-2 on bradykinin receptor signaling pathways and its role in the development of angioedema in patients taking ACE inhibitors." (PMID 38910667, 2024). "Angiotensin-converting enzyme (ACE) inhibitors are known to contribute to the development of angioedema by increasing the levels of bradykinin and its active metabolites." (PMID 38910667, 2024). "The objective of this review is to illuminate various facets of ACE inhibitor-induced angioedema within a broader context." (PMID 38543146, 2024). "ACE inhibitor-induced angioedema (AE) is clinically characterized by self-limited edema of the dermis and subcutaneous lipid tissue, localized on face skin, oral mucosa and tongue in most cases." (PMID 38543146, 2024). "Bradykinin-induced angioedema can be hereditary, acquired or drug-induced, such as with angiotensin-converting enzyme (ACE) inhibitors." (PMID 39654054, 2024). "Emerging anecdotal cases have brought attention to the intricate interaction between mTOR-Is and ACE inhibitors, leading to the development of angioedema." (PMID 38205154, 2024). "As reported for many years now, angioedema, dysgeusia, cough, hyperkalemia, renal failure, fetal malformations, and skin rashes are among the many side effects of ACE synthetic inhibitors." (PMID 39062831, 2024). "For instance, the OCTAVE trial, encompassing a vast cohort exceeding 12,000 participants, reported an incidence rate of angioedema amounting to 0.68% among individuals undergoing ACE inhibitor therapy." (PMID 38205154, 2024). "ACE inhibitor-induced angioedema is believed to result from defective degradation of at least three vasoactive peptides: bradykinin, des-Arg9-BK (a bradykinin metabolite), and substance P." (PMID 38543146, 2024). "Bradykinin is released from many cell types, and mechanisms that contribute to either its overproduction or, in the case of ACE inhibitors, its degradation, result in angioedema." (PMID 39654054, 2024). "Angioedema due to ACE-inhibitors accounts for about one-third of acute angioedema cases that present to emergency rooms in the United States." (PMID 38332896, 2024). "Most patients experience ACE inhibitor-induced angioedema a few weeks to a few months after starting an ACE inhibitor." (PMID 38910667, 2024).
angioedema (continued). "ACE inhibitor-induced angioedema occurs more frequently in African Americans, females, smokers, seniors, and those with seasonal allergies." (PMID 38910667, 2024). "This case describes a 31-year-old African American male who developed angioedema while taking an ACE inhibitor." (PMID 38910667, 2024). "This case involves a 31-year-old African American male diagnosed with coronavirus disease 2019 (COVID-19) who developed angioedema while taking an ACE inhibitor." (PMID 38910667, 2024). "Current ACE inhibitors typically inhibit both cACE and nACE, leading to a persistent cough and angioedema." (PMID 39046229, 2024). "The main strategy in managing ACE inhibitor-induced angioedema is the early discontinuation of the drug, requiring early recognition and a high level of suspicion." (PMID 38543146, 2024). "It is imperative to underscore that all these patients were concomitantly undergoing combination therapy with ACE inhibitors and displayed elevated everolimus levels at the onset of angioedema." (PMID 38205154, 2024). "All these findings underscore the intricate interplay between ACE inhibitors, mTOR-Is, and the occurrence of angioedema." (PMID 38205154, 2024). "Understanding the clinical presentation, pathophysiology, and treatment options for ACE inhibitor-induced angioedema is paramount due to its potential underdiagnosis and life-threatening nature." (PMID 38543146, 2024). "In ACE inhibitor-induced angioedema, the ACE enzyme, which also acts as the primary enzyme to break down bradykinin, is inhibited leading to increased levels of bradykinin." (PMID 39158246, 2024). "Specifically, the incidence of ACE inhibitor-induced angioedema is up to five times greater in people of African descent." (PMID 38543146, 2024). "The discontinuation of ACE inhibitors and reduction of everolimus levels, maintaining them within a range of 3–8 ng/mL culminated in the complete resolution of angioedema symptoms in six out of seven patients." (PMID 38205154, 2024). "Given that patients do not respond to anti-H1 antihistamines and steroids, early clinical recognition and discontinuation of the ACE inhibitors are the treatments of choice for the long-term management of ACE inhibitor- induced angioedema." (PMID 38543146, 2024). "A previous study reported that 0.1-0.7% of patients on ACE inhibitors develop angioedema, with up to 22-35% of those cases potentially developing significant airway obstruction." (PMID 39850167, 2024). "Patients who have shown a clear episode of ACE inhibitor-induced angioedema are recommended to be switched to a different class of anti-hypertensives to prevent the recurrence of angioedema attacks." (PMID 38910667, 2024). "The patient was treated with intravenous Solu-Medrol 60 mg every eight hours, intravenous diphenhydramine 12.5 mg every six hours, and remdesivir for suspected ACE inhibitor-induced angioedema and SARS-CoV-2 infection." (PMID 38910667, 2024). "In potentially life-threatening cases, which are often specific to a particular population group, ACE inhibitors can induce angioedema, which is characterized by swelling of the throat and tongue." (PMID 39046229, 2024). "While acknowledging limitations such as the lack of systematic methodology and the restricted search period, this review remains a valuable addition to the literature on ACE inhibitor-induced angioedema." (PMID 38543146, 2024). "In a long-term follow-up involving 111 patients with ACE-related angioedema, 46% experienced recurrent episodes after discontinuation of ACE inhibitors." (PMID 38543146, 2024). "This observed incidence concurs with recent findings from a substantial 2007 study involving 134,945 individuals, where the incidence of angioedema among patients prescribed ACE inhibitors was also reported as 0.7%." (PMID 38205154, 2024). "Bradykinin is believed to be involved in this form of angioedema, as ACE is the primary physiological pathway for bradykinin degradation." (PMID 39081961, 2024).
angioedema (continued). "There have been a few case reports of angioedema occurring in patients with concomitant ACE inhibitor use and SARS-CoV-2 infection." (PMID 38910667, 2024). "Although limited in number of subjects, elevated bradykinin levels during attacks of ACE-inhibitor dependent angioedema have actually been documented." (PMID 38332896, 2024). "According to a significant retrospective analysis, over two-thirds of angioedema episodes occur within the first trimester of commencing ACE inhibitor therapy." (PMID 38543146, 2024). "Although angioedema induced by ACE inhibitors can arise at any stage during treatment, occurring at a rate of 1 in 1000 cases, more than half of instances typically present within the initial week." (PMID 38543146, 2024). "The OCTAVE study proposed female sex, seasonal allergies, age above 65 years, a history of previous angioedema episodes, and NSAID use as potential risk factors for ACE inhibitor-induced angioedema." (PMID 38543146, 2024). "In angioedema due to ACE inhibitors (ACEi-AE), a type of AE that, like HAE-C1INH and HAE-FXII, is mediated by BK, a 1.5-fold increase in fibrinogen has been observed during attacks." (PMID 38953032, 2024). "Angioedema (AE) is a rare complication that occurs in less than 1% of those treated with ACE inhibitor therapy." (PMID 38435190, 2024). "These trials highlighted the increased incidence and severity of angioedema with omapatrilat compared with ACE inhibitors." (PMID 39046229, 2024). "It is important to consider bradykinin-mediated angioedema as a differential diagnosis, and hereditary angioedema (HAE) and certain drug-induced angioedemas (such as ACE-inhibitor-induced angioedema) are possible causes to be considered." (PMID 37920409, 2023). "Nonetheless, challenges persist in identifying biomarkers for adverse events across different antihypertensive classes, sometimes due to the rarity of certain events, such as ACE inhibitors-induced angioedema." (PMID 38108069, 2023). "With an odds ratio of 2.3, a significant predictor of angioedema was previous patient use of ACE inhibitors (95% CI 1.1 to 4.7; p=0.02)." (PMID 38957198, 2023). "It was clinically diagnosed as an angiotensin-converting enzyme (ACE) inhibitor-induced angioedema as it responded to stopping the ACE inhibitor; however, after four months, the patient again started to develop right periorbital swelling." (PMID 37073202, 2023). "Angioedema is a rare but known side effect of angiotensin-converting enzyme (ACE) inhibitor therapy." (PMID 38022184, 2023). "It should be noted that this treatment approach differs from the one used for ACE inhibitor-induced angioedema, which targets bradykinin using fresh frozen plasma and/or a bradykinin blocker such as icatibant." (PMID 37484793, 2023). "Patients who have experienced this angioedema should avoid all other ACE inhibitors in the future because this adverse effect is class-specific." (PMID 38957198, 2023). "Discontinuing the ACE inhibitor and monitoring for resolution of the angioedema confirms the diagnosis and is the mainstay of treatment in addition to airway management." (PMID 38957198, 2023). "The most common presentations of ACE inhibitor-induced angioedema describe swellings in the oropharyngeal and periorbital regions." (PMID 38022184, 2023). "The safety profile of sacubitril–valsartan was also similar to the ACE inhibitors/ARBs/conventional treatment with respect to hyperkalaemia, worsening renal function and angioedema." (PMID 36184714, 2023). "It is the accumulation of bradykinin that results in angioedema and cough which accompanies ACE inhibitor use." (PMID 38633331, 2023). "When inhibited, ACE (a component responsible for bradykinin breakdown) can trigger the accumulation of bradykinin leading to angioedema, hypotension, and bronchospasm." (PMID 36945274, 2023). "The primary adverse effects of ACE inhibitors include hyperkalemia, dry cough, angioedema, dizziness, and renal insufficiency." (PMID 37064885, 2023).
angioedema (continued). "Similar to ACE inhibitors, ARBs can result in increased bradykinin levels and subsequent angioedema, though less frequently than inhibitors." (PMID 38957198, 2023). "About 345 reports were reviewed meeting the criteria of bradykinin-mediated angioedema with concomitant ACE inhibitor and DPP-IV inhibitor use." (PMID 38957198, 2023). "We present a unique case of ACE inhibitor-induced angioedema in a 57-year-old male, which developed soon after receiving intravenous contrast." (PMID 37908932, 2023). "As documented earlier, angioedema is rare but life-threatening, so healthcare professionals should still be aware of this possible adverse consequence when ACE inhibitors are prescribed to their patients." (PMID 35886227, 2022). "Not only are cardiovascular outcomes an adverse effect in black patients taking ACE inhibitors and ARBs, but black patients are also more likely to experience angioedema when taking ACE inhibitors than other races." (PMID 36430371, 2022). "Some studies have cited up to a 77% lower incidence of cough and a 66% lower incidence of angioedema in ARBs versus ACE inhibitors." (PMID 36482421, 2022). "Icatibant has also been shown to be effective against ACE inhibitor-induced angioedema in some case series, as well as in real-life clinical experience." (PMID 35413921, 2022). "Bradykinin-mediated angioedema include angiotensin-converting enzyme (ACE)-inhibitor-induced angioedema, sartan-mediated angioedema, and hereditary angioedema (HAE) as well as angioedema due to acquired C1 inhibitor deficiency." (PMID 33643777, 2021). "ACE inhibitor-induced angioedema results from the decreased degradation of bradykinin and other vasoactive peptides such as substance P." (PMID 34884209, 2021). "On the other hand, ACE inhibitors act as a suppressor for bradykinin metabolism and increase the serum bradykinin level leading to the enhancement of angioedema pathogenesis." (PMID 34445711, 2021). "Another rare form of AAE is the angioedema exclusively induced by angiotensin-converting enzyme (ACE) inhibitors (AAE-ACEi), which affects less than 1% of patients taking this class of drug." (PMID 34956216, 2021). "In conclusion, although ACE inhibitor-induced angioedema is rare, it is difficult to determine when and in whom it will occur." (PMID 33398469, 2021). "It has been reported that the probability of ACE inhibitor-induced angioedema is higher after 65 years of age." (PMID 34284535, 2021). "Certain drugs hindering BK catabolism, such as ACE inhibitors and DPP-IV inhibitors, can cause angioedema that is usually regarded as an acquired form." (PMID 33725263, 2021). "Clinical conditions to which kinins are connected comprise angioedema and angiotensin-converting enzyme (ACE) inhibitor–induced cough, in which elevated levels of the kinin bradykinin are postulated." (PMID 33693976, 2021). "In ACE inhibitor-induced angioedema, a clinical trial and several observational studies initially suggested the therapeutic activity of icatibant, but this was not confirmed in subsequent randomized trials." (PMID 33800422, 2021). "While ACE is the major kinin-destroying peptidase in the extracellular fluid ACE inhibitor-induced angioedema is reportedly reversed by BKRB2 antagonist icatibant (51, –, 53)." (PMID 34935423, 2021). "Signals of angioedema for the following ACE inhibitors (total) (IC025: 2.19) were detected: enalapril (IC025: 2.06), imidapril (IC025: 2.38), lisinopril IC025: 1.55), temocapril (IC025: 0.29), and trandolapril (IC025: 0.19)." (PMID 34884209, 2021). "In some cases, angiotensin-converting enzyme agents also contribute to the development of bradykinin-mediated angioedema, in addition to estrogen-mediated effects of the ACE suppressive function." (PMID 34445711, 2021). "Estrogen plays a suppressive effect on ACE, resulting in the same pathway of ACE inhibitor-induced angioedema." (PMID 34445711, 2021).